CXCL2 (C-X-C motif chemokine ligand 2)
Diseases named in the same sentence as CXCL2 in open-access papers (continued):
Sharing a sentence is not in itself a finding about the gene and the disease.
acute kidney injury (7 papers, 2011 to 2025). Sudden and sustained deterioration of the kidney function characterized by decreased glomerular filtration rate, increased serum creatinine or oliguria. "SIRT2 deficiency ameliorates lipopolysaccharide-induced acute tubular injury and suppresses renal failure with decreased renal Cxcl2 mRNA expression." (PMID 29651144, 2018). "CXCL1 and CXCL2, were recently shown to be essential for neutrophil recruitment which is key to acute renal failure developing in Stx2-challenged LPS-treated mice." (PMID 21731756, 2011). "In oxalate-induced mouse models of acute kidney injury (AKI), there is evidence of inflammation in ferroptosis, inhibition of the expression of proinflammatory cytokines (including CXCL-2 and IL-6), and neutrophil infiltration." (PMID 35844784, 2022). "Moreover, we verified the differential expression of Egr1, Jun, and Cxcl2 in the IRI mouse model and acute kidney injury human samples." (PMID 38753279, 2024). "CXCL2, CCL5, and TNFα were also reduced in HuSAP+ mice (relative to WT) 48 hours after Stx2 treatment and therefore may be crucial for the inflammatory pathology leading to acute renal failure." (PMID 21731756, 2011).
colorectal tumor (7 papers, 2016 to 2025). "CXCL2 induces a dose-dependent increase in the migration of colorectal tumor cells in vitro." (PMID 41378129, 2025). "Increased expression of CXCL-type chemokines, notably CXCL1, CXCL2, and CXCL8, was observed in colorectal tumor tissues." (PMID 38979413, 2024). "CXCL1 is highly expressed in human colorectal tumors, and both CXCL1 and CXCL2 are involved in IBD and believed to promote tumor angiogenesis by directly activating their shared receptor, CXCR2, on endothelial cells." (PMID 29720595, 2018).
endometriosis (7 papers, 2018 to 2025). The growth of functional endometrial tissue in anatomic sites outside the uterine body. "Overexpression of CXCL2 has been detected in the peritoneal fluid of women with endometriosis, contributing to the pro-inflammatory peritoneal environment." (PMID 41378097, 2025). "When miR-215-5p is silenced or downregulated (as in endometriosis), CXCL2 is overexpressed, which can facilitate the progression of endometriotic lesions by enhancing inflammation and neovascularization." (PMID 41378097, 2025). "We speculate that the silencing effect of miR-215-5p on its target gene CXCL2 is weakened in women with endometriosis, which results in high expression of CXCL2 and supports the progression of endometriosis." (PMID 34542679, 2022). "Studies have found that CXCL2 pathway activation can lead to the release of inflammatory mediators such as protease, prostaglandin (PG), leukotriene (LT), and reactive oxygen species intermediates, and expression of CXCL2 is high in the peritoneal fluid of patients with endometriosis." (PMID 34542679, 2022). "Consistently, patients with endometriosis displayed a significant higher production of CXCL1, CXCL2, and CXCL8 in the peritoneal fluid as compared to those from controls." (PMID 32334621, 2020). "Similarly, in the peritoneal fluid of women with endometriosis, levels of CXCL1, CXCL2, CCL2, MCP-3, and HGF were found to be significantly elevated compared to those in control individuals." (PMID 31636643, 2019). "Moreover, transient inhibition or reduction of miR-223 expression exacerbated endometriosis, as indicated by the histological indices, increased NLRP3, IL-1β, IL-6, and TNF-α secretion, as well as the IL-1β-inducible chemokines CXCL1 and CXCL2 mRNA transcripts." (PMID 30186287, 2018).
ischemia (7 papers, 2013 to 2024). A hypoperfusion of the BLOOD through an organ or tissue caused by a PATHOLOGIC CONSTRICTION or obstruction of its BLOOD VESSELS, or an absence of BLOOD CIRCULATION. "It regulates the expression of proteins such as IL1B (interleukin-1 beta) and CXCL2 (C-X-C motif chemokine ligand 2) involved in the inflammatory process and the development of tissue damage after ischemia." (PMID 38956704, 2024). "Various chemokine receptors, such as CCR2 with the ligand MCP-1 and CXCL2 with multiple ligands, such as Groα, Groβ and IL-8, are up-regulated in brain lesions of trauma, ischemia, and multiple sclerosis (MS)." (PMID 24691121, 2014). "In the setting of MI, chemokines that recruit PMNs to sites of ischemia include macrophage inflammatory protein-2α (MIP-2α, CXCL2, GRO β), leukotriene B4 (LTB4), CINC-1 (CXCL1, GRO α, KC), IL-8 (CXCL8), and complement 5a." (PMID 23731794, 2013). "This past study demonstrated an increase in total lung CXCL2 within the first day after the onset of ischemia and an inhibitory effect of anti-CXCR2 on bronchial angiogenesis." (PMID 23776670, 2013). "In a mouse model in which ischemia was pharmacologically induced, it was observed that TREM-1 promotes the production of IL-1β, IL-18, IL-6, CXCL-2, MCP-1, and CXCL-1 in microglia." (PMID 39062850, 2024). "Consistently, we found that ischemia-induced TREM-1 promoted IL-1β, IL-18, IL-6, CXCL-2, MCP-1, and CXCL-1 productions in microglia as well as the expression of MPO and ICAM-1 following ischemic injury." (PMID 31324751, 2019).
liver cancer (7 papers, 2022 to 2025). An epithelial or non-epithelial malignant neoplasm that arises from the liver. "CXCL2 and CXCL10 are genes enriched by Chemokine signaling pathway; CXCL2 promotes the proliferation and metastasis of liver cancer cells; and CXCL10 is associated with enhanced T cell infiltration in tumors." (PMID 35463358, 2022). "In liver cancer, however, CXCL2 again plays a very different role." (PMID 38021148, 2023).
neuroblastoma (7 papers, 2019 to 2025). Neuroblastoma (NB) is the most common solid, extracranial childhood tumor. "In the microenvironment of neuroblastoma, the CXCL2/CXCR2 axis enhances the invasiveness of the tumor via the macrophage-derived signal, justifying the rationale of targeting CXCR2 in NB." (PMID 41155662, 2025). "PS suppressed the levels of IL-6, IL-10, CXCL1, and CXCL2 induced by paclitaxel in a neuroblastoma cell line, and macrophage activation to the M1 proinflammatory phenotype." (PMID 38347876, 2023). "Moreover, macrophage-derived CXCL2 promoted neuroblastoma invasiveness, but CXCL2/CXCR2 mechanism in this context remains unclear." (PMID 38087370, 2023). "In co-cultured murine neuroblastoma and microphage cell lines (Neuro-2A and RAW264.7) that mirror the inflammatory infiltrate of CIPN, we evaluated the effect of PS on the expression of four cytokines, IL-6, IL10, CXCL-1, and CXCL-2, all involved in CIPN." (PMID 38347876, 2023).
pneumococcal infection (7 papers, 2015 to 2024). Infections with bacteria of the species streptococcus pneumoniae. "The massive production of cytokines such as TNF-α, IL-6, IL-12, CXCL1, and CXCL2 was a hallmark of the secondary pneumococcal infection after the flu." (PMID 29326698, 2017). "We subsequently measured G-CSF, CXCL1 and CXCL2 transcript levels in the lungs during high inoculum pneumococcal infection." (PMID 31776393, 2019). "We found that, following pneumococcal infection, the level of pulmonary CXCL-2 was significantly elevated in CD73-/- mice compared to wild-type mice." (PMID 26313746, 2015). "In assessing whether EAD regulated some of the key molecules implicated in PMN recruitment into the lungs during pneumococcal infection, we found by ELISA that upon infection, CD73-/- mice had 7-fold higher levels of the chemokine CXCL2 in their lungs than did wild type mice." (PMID 26313746, 2015). "In another study, pneumococcal infection was shown to trigger the release of IL-1β following the induction of CXCL1 and CXCL2 in epithelial cell." (PMID 38664730, 2024). "One study reported that IL-12 administration can improve innate defenses against pneumococcal infection by inducing IFN-γ and CXCL2 production, and thereby increasing the recruitment and activation of neutrophils." (PMID 37958756, 2023). "Luminex-based analyses of pro- and anti-inflammatory cytokines showed significantly increased levels of CXCL1, CXCL2 and G-CSF in BALF of S100A9 KO mice as compared to WT mice on days 1 and 2 after pneumococcal infection." (PMID 37467233, 2023).
Salmonella Infections (7 papers, 2011 to 2025). Infections with bacteria of the genus SALMONELLA. "Confirming the initiation of an epithelial immune response by the intestinal barrier model, Salmonella infection induced the expression of both coding (SOCS3, CXCL2, CXCL3) and noncoding (NEAT1) immune-associated RNAs in IECs." (PMID 32071273, 2020).
acne (6 papers, 2010 to 2024). An inflammatory process of the sebaceous glands which is characterized by comedones, nodules, papules and/or pustules on the skin. "The chemokine CXCL1 (Keratinocyte derived chemokine-KC) is upregulated in acne, acting as neutrophil chemoattractant, and CXCL2 (SDF-1)—produced by macrophages—is also upregulated and operates to attract polymorphonuclear leukocytes." (PMID 35910763, 2022). "All these genes encode proinflammatory cytokines and chemokines previously detected in acne lesions and are linked to activation of the NF-κB pathway, inducing the upregulation of TNF-α, CXCL8/IL-8, IL-1β, CXCL1 and CXCL2." (PMID 35563458, 2022). "CXCL1/keratinocyte-derived chemokine (KC), CXCL2/MIP2 and CXCL5-6/lipopolysaccharide-induced CXC chemokine (LIX) were regarded as functional homologues of IL-8, where CXCL1, CXCL2 and CXCL6 are identified as candidates associated with acne pathogenesis in humans." (PMID 32707723, 2020).
autoimmune disease (6 papers, 2017 to 2023). A disorder resulting from loss of function or tissue destruction of an organ or multiple organs, arising from humoral or cellular immune responses of the individual to their own tissue constituents. "CXCL1, CXCL2, and CXCL8/IL-8 are contributors to granulocyte and leukocyte migration, particularly in other autoimmune diseases such as multiple sclerosis and experimental autoimmune encephalomyelitis." (PMID 35885983, 2022). "It has been widely reported in the literature that many cytokine and chemokine genes (e.g., TNF-a, IL-8, CXCL2, CXCL3, CXCL10, LIF, IL-17C and IL-23A) are the basis of autoimmune disorder pathways that are characterized by inflammation." (PMID 28099447, 2017). "For instance, in the case of autoimmune diseases, such as multiple sclerosis or experimental autoimmune encephalomyelitis, neutrophils are known to be attracted by the release of CXCL1, CXCL2, and CXCL5, which are in turn stimulated by different molecules, such as IL-17 or IFN-γ." (PMID 33364241, 2020). "In autoimmune diseases, it was found TCRαβ+ DNT cells might arise from CD8+ T cells and displayed a distinct cytokine production profile by producing proinflammatory mediators that include IL-1β, IL-17, IFN-γ, CXCL3, and CXCL2." (PMID 36443691, 2022).
Autoimmunity (6 papers, 2012 to 2024). The occurrence of an immune reaction against the organism's own cells or tissues. "Reducing ALKBH5 resulted in heightened m6A modification on IFNG and recombinant human C-X-C motif chemokine 2 (CXCL2) mRNA, impairing CD4+ T cell responses and contributing to the suppression of autoimmunity." (PMID 39072324, 2024). "During autoimmunity, ALKBH5 increases the m6A modification of IFN-γ and C-X-C motif chemokine ligand 2 (CXCL2), leading to decreased mRNA stability and protein levels in CD4+ T cells, according to a recent study." (PMID 37217462, 2023). "IL-17 plays a key role in chronic inflammatory disorders and autoimmunity, and this cytokine stimulates chemokines (e.g., CXCL1, CXCL2 and CXCL8) and granulopoiesis." (PMID 35641947, 2022).
dermatitis (6 papers, 2016 to 2025). An inflammatory process affecting the skin. "IL-1β and CXCL2 have been demonstrated to play pivotal roles in the pathogenesis of dermatitis." (PMID 41296413, 2025). "HFD reduced mRNA levels of IL-17A, IL-17F, IL-22, IL-1β, tumor necrosis factor (TNF)-α, CXCL1, CXCL2, and keratin 16 and increased those of transforming growth factor (TGF)-β1 and cyclin-dependent kinase inhibitor 1A in imiquimod-induced dermatitis." (PMID 37762500, 2023). "The HFD decreased mRNA expression of IL-17A, IL-17F, IL-22, TNF-α, IL-1β, CXCL1, CXCL2, and keratin 16, and increased mRNA expression of TGF-β1 and CDKN1A in imiquimod-induced dermatitis." (PMID 37762500, 2023). "Oral propionate and the HFD reduced mRNA expression of IL-17A, IL-17C, IL-17F, IL-22, IL-1β, IL-6, TNF-α, CXCL1, CXCL2, and CCL20 in imiquimod-induced dermatitis." (PMID 37762500, 2023). "In imiquimod-induced dermatitis, IL-17A, IL-17F, and IL-22 may be mostly derived from Th17 cells or γδT17 cells, while CXCL1, CXCL2, CCL20, and IL-17C may be mainly produced by epidermal keratinocytes." (PMID 37762500, 2023).
experimental autoimmune encephalomyelitis (6 papers, 2020 to 2022). An autoimmune demyelinating disease of the central nervous system that is produced experimentally in animals by the injection of homogenized brain or spinal cord in Freund's adjuvant. "A very recent study showed that ALKBH5 deficiency decreased the mRNA stability and protein secretion of IFN-γ and C-X-C motif chemokine ligand 2 (CXCL2) in CD4+ T cells, thereby alleviating experimental autoimmune encephalomyelitis." (PMID 35296338, 2022). "In an experimental autoimmune encephalomyelitis mouse model, ALKBH5 decreased m6A modification on interferon-γ (IFN-γ) and C-X-C motif chemokine ligand 2 (CXCL2) mRNA in CD4+ T cells, increasing the stability of mRNA transcripts and enhancing corresponding protein expression." (PMID 35897696, 2022). "In addition, Th17 cells are also capable of inducing CXCL1 and CXCL2, chemokines that are powerful attractants for polymorphonuclear cells, and of contributing much to the disruption of the BBB in experimental autoimmune encephalomyelitis (EAE)." (PMID 33281728, 2020).
fungal infection (6 papers, 2015 to 2026). "CXCL8 and CXCL2 are critical chemokines involved in neutrophil recruitment and activation, which play a vital role in the host’s pro-inflammatory immune response to fungal infections." (PMID 41081505, 2025). "It has been reported that a number of major SNPs are associated with susceptibility of fungal infections and diseases, including MBL2, TLR1/4/6/9, CARD9, CXCL2, DECTIN1, IL4/10/15/2, and HLA." (PMID 33362211, 2020). "First, lung and airway CXCL1 levels increase more rapidly than CXCL2 levels at the onset respiratory fungal infection and thus CXCR2-dependent trafficking steps may reflect the relative abundance of cognate ligands." (PMID 25621893, 2015). "Since the patient’s neutrophils did not exhibit a primary chemotaxis defect, we next measured levels of the neutrophil-targeted chemokines CXCL1, CXCL2, CXCL5 and IL-8 in the infected CSF by Luminex array at different prospective time-points during uncontrolled fungal infection." (PMID 26679537, 2015).
lymph node metastasis (6 papers, 2022 to 2024). "In this work, lymph node metastasis in skin cutaneous melanoma was associated with CXCL2, in liver hepatocellular carcinoma with CXCL5, in kidney renal clear cell carcinoma with PPBP, and in esophageal carcinoma with CXCL8/IL-8." (PMID 37686093, 2023). "In addition, CXCL2 expression has been positively correlated with lymph node metastasis." (PMID 37893029, 2023).
ovarian tumor (6 papers, 2015 to 2021). "However, by analyzing the gene data of GSE114206 dataset and TCGA database, it showed no statistically significant in correlation of CXCL2 and ATR/CHK1 expression in ovarian tumor." (PMID 34474677, 2021).
peritonitis (6 papers, 2017 to 2023). Inflammation of the peritoneum (tissue that lines the abdominal wall and covers most of the organs in the abdomen). "In addition, the concentration of pro-inflammatory cytokines TNF-α, IL-6, IL-1β, KC (CXCL1) and MIP-2 (CXCL2) within the peritoneal lavage also demonstrated that SEMA7A holds protective potential during peritonitis." (PMID 38094294, 2023). "To test if observed defective expression of Cxcl1 and Cxcl2 in lmp7−/− mice has an impact on recruitment of inflammatory cells during peritonitis, we measured the percentage of neutrophils in peritoneal lavages 4 h after intraperitoneal injection of thioglycollate." (PMID 28881574, 2017). "Moreover, we would suggest that Nrf2 activation in zymosan-induced peritonitis could limit neutrophil activation and auto-recruitment mainly via the regulation of TNFα, CXCL2 and CCL3 production in the peritoneal fluid." (PMID 31419224, 2019). "MSCs spheroids decreased neutrophil activity, the levels of the pro-inflammatory molecules TNF-α, IL-1β, CXCL2/MIP-2, PGE2, and plasmin activity in a mouse peritonitis model." (PMID 30564236, 2018). "The migration of neutrophils into the peritoneal cavity during induction of peritonitis has been described to be mediated via CXCL1 and CXCL2." (PMID 28881574, 2017).
adenoma (5 papers, 2011 to 2025). A neoplasm arising from the epithelium. "Among pro-inflammatory cytokines, CXCL2 expression was significantly lower in adenocarcinomas (p = 0.007), with paired analysis confirming this trend (67% of samples exhibited higher expression in adenomas, p = 0.0002)." (PMID 40699620, 2025). "In previous studies, a highly significant upregulation of CXCL2 chemokine was found in CRC compared to normal colonic mucosa which could be already detected also in benign adenoma referring to the involvement of CXCL2 in the dysplasia-carcinoma transition." (PMID 23155391, 2012). "Except for CXCL2, which was upregulated in lesions as compared to normal mucosa regardless of polyp type, other genes presented changes in opposite direction in hyperplastic polyps (an upregulation in lesions) and polyps from traditional adenoma-carcinoma sequences (a downregulation in lesions)." (PMID 38338661, 2024). "In adenomas, only CCL4 was expressed at comparable level between the lesion and paired normal mucosa, while the expression of CCL3 (p = 0.006), CXCL2 (p = 0.023) and CCL19 (p = 0.016) was significantly higher in lesions." (PMID 38338661, 2024). "CXCL1, CXCL2, CXCL3, CCL20, and IL-8 had increased expression in the adenoma and adenocarcinoma compared to normal colonic mucosa." (PMID 21249124, 2011). "Finally, we found that SASP transcripts were elevated in about 59–61% of adenomas, both using two SASP signatures and a single-gene level that included genes such as CCL2, CXCL2, FOXO4, and NKFB1 and 2, highlighting the proinflammatory milieu often accompanying OIS." (PMID 40699620, 2025).
esophageal squamous cell carcinoma (5 papers, 2015 to 2026). Esophageal squamous cell carcinoma (ESCC) is a type of esophageal carcinoma (EC) that can affect any part of the esophagus, but is usually located in the upper or middle third. "A study in esophageal squamous cell carcinoma showed that inflammation or immune-related TLR4, IL-8, IL-6, and chemokine (C-X-C motif) ligand 2 (CXCL2) were increased upon PLCE1 suppression." (PMID 35054579, 2021).